SNORD58B (small nucleolar RNA, C/D box 58B)
Synonyms: U58b; RNU58B
Gene: Small nucleolar RNA gene on chromosome 18 (49,491,664 to 49,491,729, reverse strand). Ensembl gene ENSG00000271982.
Gene Ontology:
Biological process: RNA processing
Cellular component: nucleolus
Homologues: Orthologues: macaque SNORD58 (98% identical), guinea pig SNORD58B (92% identical), mouse Gm22354 (91% identical), mouse Snord58b (91% identical), rabbit SNORD58B (91% identical), rat Snord58b (91% identical), dog SNORD58 (88% identical). Paralogues in human: SNORD58 (91% identical), SNORD58A (79% identical), SNORD58C (73% identical).